CXCL9 (C-X-C motif chemokine ligand 9)
Diseases named in the same sentence as CXCL9 in open-access papers (continued):
Sharing a sentence is not in itself a finding about the gene and the disease.
glioma (34 papers, 2013 to 2025). A benign or malignant brain and spinal cord tumor that arises from glial cells (astrocytes, oligodendrocytes, ependymal cells). "In vitro application of the oncometabolite α-hydroxyglutarate (α-HG), typical of IDH-mutated gliomas, confirmed its direct effect on reduced expression of the chemokines CXCL9 and CXCL10 and thus on reduced migration of CD8+ T cells." (PMID 38275375, 2023). "Most of the chemokines that have been shown to regulate glioma angiogenesis, such as CXCL9 and CXCL10, are highly expressed in cluster B." (PMID 38181024, 2024). "Chemokines associated with T cell trafficking (CCL3, CCL5, CXCL9, and CXCL10) were all upregulated in KR158B glioma tissue compared to naïve tissue." (PMID 39272914, 2024). "In gliomas with a mutation of the isocitrate dehydrogenase gene (IDH-mutation), decreased expression of the T cell-attracting chemokines CXCL9 and CXCL10 was found, resulting in reduced migration of CD8+ T cells to tumors in vitro." (PMID 38275375, 2023). "In gliomas, abnormal expression profiles of CXCL9, CXCL10, CXCL11, and CXCL12 were noticed among different pathological grade gliomas, implying their potential relationship with glioma progression." (PMID 34603309, 2021). "Lymphocyte infiltrates expressed CXCR3/6 and CCR6, but the CXCR3 ligands CXCL9/10/11 were rarely detected in glioma samples with the exception of interferon-activated microglia." (PMID 34692159, 2020). "Gene expression of CXCL9 and 10 by qRT-PCR was determined in human and murine gliomas cell lines after treatment with a combination of IFNg and GSK126." (PMID 30400835, 2018). "From a mechanistic point of view, we suggest that STAT3 activation and the release of CXCL9/10 are suitable candidates to answer the question of how microglia supports glioma growth." (PMID 26157361, 2015). "In another study, CXCL9 induced cancer cell growth in an in vitro model of human and murine glioma." (PMID 40362215, 2025). "Importantly, PD-1 blockade induced an IFN-γ gene signature in glioma-infiltrating monocytes and macrophages that was reflected by the expression of CXCL9/10 and PD-L1." (PMID 35784281, 2022). "Levels of the Ifnb1, Cxcl9, Cxcl10 and TNF-α mRNAs in glioma tissues from different treatment groups were determined using qRT-PCR to evaluate the activation of STING signaling." (PMID 35386310, 2022). "In a mouse glioma model, brain tumor-infiltrating macrophages also expressed CD169 and produced the proinflammatory chemokines CXCL9, CXCL10, and CXCL16." (PMID 36266311, 2022). "In this work, CXCL9, CXCL10, and CXCL14 were also identified as potential vital regulators of glioma progression among the CXCL family." (PMID 34603309, 2021). "TIME cluster A exhibited the high expression profiles of ZEB1, TNF, and LAG3; while GZMA, CXCL9, CXCL10, and CD8A were relatively overexpressed in TIME cluster C. EMT is a common process of paramount importance in glioma occurrence and invasion." (PMID 34650972, 2021). "The data shown in our study indicate that overexpressed JMJD1C increases the expression of M1 markers (IL‐1β, TNF, CXCL9, IL‐23, ROS1, IL‐12a, and IL‐12b) both in the glioma mouse models and in the CD14+ monocytes co‐cultured with glioma cells." (PMID 34586733, 2021). "Our group and others have found that CXCR3, along with its ligands CXCL9 and CXCL10, plays predominant roles in cytotoxic lymphocyte trafficking into the glioma tumor site." (PMID 30740109, 2018). "CXCL9 and CXCL10 were enhanced both at the RNA and protein level in glioma cells treated with IFNg and GSK126 compared to vehicle treatment." (PMID 30400835, 2018). "Of interest, both in vitro and in vivo experiments using different glioma tumors, including GL261 cells, indicated CXCL9 and CXCL10 (which bind to their endogenous receptor CXCR3) as key ligands promoting the growth of glioma." (PMID 26157361, 2015).
glioma (continued). "In addition, the levels of CXCL9, CXCL10, and CCR3, which increase the recruitment of CD8+ T cells into the microenvironment of glioma, were increased in gliomas with high TANK expression." (PMID 37215097, 2023). "In the training cohort, CXCL14 (P value < 0.001), CXCL9 (P value < 0.05), CXCL10 (P value < 0.001), CXCL11 (P value < 0.001), CXCL6 (P value < 0.001), and CXCL1 (P value < 0.001) were enriched in the IDH wide-type gliomas." (PMID 34603309, 2021). "CXCL9, CXCL10, CXCL11, CXCL12, and CXCL14 were filtered as main contributors of glioma progression." (PMID 34603309, 2021). "In gliomas, the IDH1 mutation has a negative impact on the immune system resulting in reduced Natural Killer ligands and decreased tumor lysis, as well as decreased chemokines CXCL9, CXCL10 with subsequent reduction in the number of CD3+ CD8+ tumor infiltrating lymphocytes." (PMID 35664748, 2022).
psoriasis (34 papers, 2009 to 2026). An autoimmune condition characterized by red, well-delineated plaques with silvery scales that are usually on the extensor surfaces and scalp. "Similar to CCL2, CXCL9 has been reported to participate in monocyte proliferation associated disease, including psoriasis." (PMID 28787010, 2017). "Moreover, mediators secreted by γδ T cells activate KCs to produce multiple psoriasis-associated mediators, including NF-α, IL-6, CXCL9, CXCL10, and AMPs." (PMID 38642273, 2024). "A study conducted in 2009 involving 13 patients with psoriasis induced by TNFi drugs found that there was a higher expression of CXCL9 in the epidermis of psoriasiform lesions than in healthy control skin and psoriasis patients." (PMID 39000125, 2024). "IL-1β promotes the differentiation of Th17 cells to secrete IFN-γ, and IL-18 enhances IFN-γ-induced production of C-X-C motif chemokine 9 (CXCL9), CXCL10 and CXCL11, which migrate from dermis to epidermis causing chronic inflammatory activation of psoriasis." (PMID 39689159, 2024). "The expression of chemokines and their receptors are regulated by psoriasis-associated cytokines, including IL-17 which upregulates CCL2, CCL7, CCL20, and CXCL1, or IFN-γ which upregulates CXCL9 and CXCL10." (PMID 38642273, 2024). "Therapies frequently used in psoriasis patients such as dimethylfumarate or apremilast can inhibit chemokines like Cxcl9 and Cxcl10, which highlights the role of these two chemokines in psoriasis." (PMID 34440590, 2021). "Results suggested that the higher the expression of CXCL9 and SPRR1B, the greater the risk of psoriasis." (PMID 34134787, 2021). "These include the chemokine Cxcl9 and Cxcl10 genes as typical molecular LP markers that distinguish lichenoid tissue reactions from atopic dermatitis and psoriasis." (PMID 31447864, 2019). "In psoriasis miR-17 and the other members of the miR-17-92 cluster induce the release of C-X-C motif chemokine ligand 9 and 10 (CXCL9; CXCL10) from keratinocytes by targeting SOCS1, thus increasing inflammation because of the T cells attraction." (PMID 30322050, 2018). "The mean percentages of inflammatory cells from psoriasis skin lesions expressing CXCL9, CXCL10, CXCL11 and CXCR3 were 3.0% ± 3.4%, 3.0% ± 2%, 46.8% ± 17.7% and 21.2% ± 19.5%, respectively." (PMID 28436448, 2017). "Notably, LCs in psoriasis patients exhibit upregulation of C-X-C motif chemokine ligand 9 (CXCL9), which mediate the targeted recruitment of T lymphocytes to inflammatory foci, thereby amplifying the psoriatic immune cascade." (PMID 41009795, 2025). "Furthermore, the transcriptional signature from affected skin revealed upregulation of key human psoriasis genes, including Lcn2 and Defb4, cytokines Tnf, Il1b, and Il36a/g, and chemokine ligands Ccl2, Cxcl9, and Ccl20." (PMID 38528069, 2024). "Real-time PCR results further confirmed that the mRNA levels of psoriasis-related factors keratin-17, integrin β1, and CXCL9, as well as the mRNA levels of inflammation-related factors IL-1β, IL-6, TNF-α and iNOS, were strongly inhibited in skin of Mincleflox/flox/Lyz-cre+/+ mice." (PMID 37117184, 2023). "Similar to other related immune-mediated skin disorders, such as psoriasis, the miRNA17-92a-1 cluster promotes chemokines, such as CXCL9 and CXCL10, in keratinocytes and further T cell chemotaxis by inhibiting the expression of suppressor of cytokine signaling 1 (SOCS1)." (PMID 35328059, 2022). "Importantly, CXCL9 and SPRR1B, as well as methylation markers TGM6 and S100A9, have an impact on the risk of psoriasis." (PMID 34134787, 2021). "Excitingly, Ebosin could significantly suppress the production of CXCL-9 in preliminary experiments, which is a key indicator of psoriasis." (PMID 33981308, 2021). "Interestingly, we found that Ebosin could reduce IFNγ-induced CXCL-9 level in HaCaT cells, which is a key evaluated indicator for psoriasis." (PMID 33981308, 2021). "Among them, high expression of CXCL9 and SPRR1B may be risk factors for psoriasis." (PMID 34134787, 2021).
psoriasis (continued). "This study explores the regulatory roles and mechanisms of chemokines CXCL9, CXCL10, and CXCL11 in psoriasis." (PMID 40303401, 2025). "Multiple chemokines have higher expression levels within the lesion-prone skin of psoriasis sufferers, including the CXC chemokine family members CXCL9, CXCL10, and CXCL11, with increased expression of CXCL9/10 being characteristic of psoriasis." (PMID 40303401, 2025). "Proteins related to the central disease‐driving pathways of psoriasis, namely the TH1 (CCL3, CCL4, CXCL9, CXCL10, CXCL11, TNFα) and TH17 pathway (CXCL1, CCL20, IL‐17A, IL‐12B) were found elevated in lesional skin across both studies." (PMID 40970551, 2025). "A number of serum analytes identified by Olink analysis, including PI3, IL-17C, CCL20, IL-20, IL-6, CXCL9, and CXCL10, have been previously identified as being elevated in serum samples of patients with psoriasis." (PMID 39224116, 2024). "In addition to those previously noted, cytokines like IFN-γ, TGF-β, CXCL9, CXCL10, IL-33 and CXCL11 play a significant role in psoriasis pathogenesis." (PMID 40303401, 2025). "CXCL9, SPRR1B, TGM6 and S100A9 may be potential targets for the diagnosis and treatment of psoriasis." (PMID 34134787, 2021). "Notably, some of them, including CXCL9 and CXCL10, are upregulated even in non-lesional skin of psoriasis patients which may contribute to the initiation of novel skin lesions." (PMID 38642273, 2024).
colon carcinoma (33 papers, 2009 to 2025). "In a colon cancer model with a heterogeneous response to avelumab (anti-PD-L1), single-cell RNA sequencing on biopsies before treatment allowed the discovery of a Cxcl9+ macrophage subset which is associated with the response." (PMID 36429101, 2022). "The administration of heterodimeric IL-15 into colon cancer-bearing mice led to increased levels of XCL1 as well as the IFN-γ-induced chemokines CXCL9/10." (PMID 38928238, 2024). "The recruitment of T cells in human colon cancer tissue was impacted by CXCL9 and CXCL10, whose expression is regulated by H3K27me3 repression marks." (PMID 37273004, 2023). "Upregulated cyclin G2 inhibited lung and colon cancer growth by increasing the secretion of its downstream effector CXCL9, which promoted CTL chemotaxis and suppressed vascular endothelial cell tube formation." (PMID 36566226, 2022). "It has been shown that expression of CXCL9/MIG is higher in patients with colon cancer as compared to healthy controls." (PMID 34611474, 2021). "We found that loss of IL-17 signaling resulted in increased levels of the T cell-attracting chemokines CXCL9, 10, and 11 in colonic tumors." (PMID 31775909, 2019). "The expression of CXCR3 receptors by human and murine colon carcinoma cells has led us to determine the ability of the corresponding ligands (mouse CXCL9, CXCL10 and CXCL11) to induce their migration in vitro." (PMID 19436305, 2009). "Recent studies indicate that in colon cancer tissues, CXCL9 expression levels are significantly higher than in normal colonic tissues and are notably associated with tumor differentiation, invasion, lymph node metastasis, distant metastasis, and vascular invasion." (PMID 38791448, 2024). "Importantly, high CXCL9 expression correlates positively with colon cancer patient survival rates, suggesting its potential as an independent prognostic factor." (PMID 38791448, 2024). "Thus, the electroporation of established colon tumors with a plasmid coding for CXCL9 together with IL-12 increases the CD8 T-cell recruitment and delays the tumor growth, either alone or in combination with an anti-PD-1 Ab." (PMID 36429101, 2022). "Moreover, the association of cyclophosphamide with a TLR9 agonist increases the chemokine expression in murine colon tumors (Ccl5, Cxcl9 and Cxcl10) and CD8 T-cell proportion and inhibits tumor growth." (PMID 36429101, 2022). "For example, high expression of CXCL9 and CXCL10 is associated with increased numbers of tumor infiltrating CD8+ T cells, decreased metastasis, and improved survival in patients with ovarian and colon cancers." (PMID 31927532, 2020). "In MC38 colon tumors, repeated anti-CD40 or radiotherapy created necrosis that split TAMs into peripheral Cxcl9+ and peri-necrotic Spp1+ subsets." (PMID 41176316, 2025). "We further explored CXCL9-Fc and CXCL10-Fc therapy in the CT26 colon cancer model in WT Balb/C mice." (PMID 39474427, 2024). "CXCR3+ NK-cell and CD8+ T-cell tumoral infiltration, directed by CXCL9 and CXCL10, can delay primary tumor growth in MC38 colon carcinoma and TC-1 epithelial carcinoma mouse models when treated with heterodimeric IL-15." (PMID 36030223, 2022). "However, in contrast to its ligands, CXCL9, CXCL10, and CXCL11, the protein expression of the CXCR3 chemokine receptor protein in colon cancer tissue could be associated with increased tumor size, the occurrence of lymph node or distant metastasis, and poor survival." (PMID 36428508, 2022). "When the gene expression level of PD-L1 was analyzed, we also observed a positive correlation between CXCL9 expression and CD274 expression in our CRC cohort, which was supported by the data of colon cancer and rectal cancer cohort from TCGA." (PMID 36362062, 2022). "Initial quantitative PCR studies of ex vivo tissue specimen showed that CXCL9, CXCL10 and CXCL11 are significantly increased in human colon tumors compared to unaffected tissue." (PMID 29671006, 2018).
colon carcinoma (continued). "Cumulative evidence suggested that increased expression levels of CXCL9 and CXCL10 induced tumor-infiltrating CD8+T cells, leading to reduced cancer progression or metastasis and enhanced survival in ovarian and colon cancer patients." (PMID 30034618, 2018). "CXCL9 and CXCL10 were identified as T-cell homing factors in colon cancer, and increased CXCL11 expression is a marker for less aggressive disease." (PMID 29163806, 2017). "We previously identified chemokines CXCL9, CXCL10, and CXCL11, as well as GZMB (Granzyme B), as part of a prognostic gene signature in colon cancer." (PMID 29163806, 2017). "Interestingly, in a colon cancer mouse model, the immune-suppressive effect of TGF-β1 has been shown to be involved in repression of CXCL9 and CXCL10 expression in CAFs, which subsequently inhibited the recruitment of effector T cell infiltration into tumors." (PMID 38580966, 2024). "When CXCL9 and immunostimulatory factor OX40 ligand were delivered into a colon cancer mouse model via lentivirally transduced mesenchymal stem cells (MSCs), increased numbers of CD8+ T and NK cells and an improved efficacy of the anti-PD-1 treatment were observed." (PMID 38928238, 2024). "T helper 1-type chemokines CXCL9 and CXCL10 are silenced by PRC2 in ovarian and colon cancer." (PMID 35169119, 2022). "Hence, using MSC engineering to deliver CXCL9 (and also immunostimulatory factors OX40L and TNFSF4) triggers an increase in the CD8 and NK cells expressing granzyme B in colon tumor models." (PMID 36429101, 2022). "However, there have also been reports of CXCL9, CXCL10, and CXCL11 that promote tumor proliferation in colon cancer, esophageal adenocarcinoma, and head and neck cancer by promoting inflammation or other mechanisms." (PMID 32685487, 2020). "Earlier studies reported a prognostic role for CXCL9 and CXCL10 expression in colon cancer." (PMID 29163806, 2017). "Along that line, high expression of CXCL9 and CXCL10, but not CXCL11, was associated with the attraction of memory CD8 T-cells with a specific TCR repertoire in colon cancer, indicative of good prognosis." (PMID 29163806, 2017). "Therefore, the chemokine, CXCL9, and UBD, which is a marker of immune activation in hepatocellular carcinoma and colon carcinoma, are preferentially induced by type II interferon in both professional immune and non-immune cells." (PMID 20339534, 2010). "To date, enhancing the CXCL9/10/11-CXCR3 chemokine axis by administering recombinant CXCL9/10/11 proteins or using expression vector systems has demonstrated positive outcomes in various pre-clinical tumor models, including skin, lung, kidney, and colon tumors." (PMID 40867314, 2025). "CXCL9 and CXCL10 are endogenous tumor angiogenesis inhibitors and high levels of CXCL9 and CXCL10 promote increasing numbers of tumor-infiltrating CD8+ T cells and reduce the level of cancer metastasis and improve survival rate of patients with ovarian or colon cancer." (PMID 36387070, 2022). "To further investigate these chemokines in human CRC, we characterized the cells producing CXCL9 and 10 ex vivo without any stimulation, and found that human endothelial cells (defined as CD31+CD105+ cells) in colon tumors produce both chemokines." (PMID 29671006, 2018).